AK6 (adenylate kinase 6)
Description:
Broad-specificity nucleoside monophosphate (NMP) kinase that catalyzes the reversible transfer of the terminal phosphate group between nucleoside triphosphates and monophosphates. Also has ATPase activity. Involved in the late cytoplasmic maturation steps of the 40S ribosomal particles, specifically 18S rRNA maturation. While NMP activity is not required for ribosome maturation, ATPase activity is. Associates transiently with small ribosomal subunit protein uS11. ATP hydrolysis breaks the interaction with uS11. May temporarily remove uS11 from the ribosome to enable a conformational change of the ribosomal RNA that is needed for the final maturation step of the small ribosomal subunit (By similarity). Its NMP activity may have a role in nuclear energy homeostasis. AMP and dAMP are the preferred substrates, but CMP and dCMP are also good substrates. IMP is phosphorylated to a much lesser extent. All nucleoside triphosphates ATP, GTP, UTP, CTP, dATP, dCTP, dGTP, and TTP are accepted as phosphate donors. CTP is the best phosphate donor, followed by UTP, ATP, GTP and dCTP. May be involved in regulation of Cajal body (CB) formation.
Synonyms: hCINAP; CINAP; AD-004; CGI-137; CIP
Tractability: Small molecule: a structure with a bound ligand is known; it has a high-quality binding pocket. PROTAC: ubiquitination databases record sites on it.
Gene: Protein-coding gene on chromosome 5 (69,350,984 to 69,370,013, reverse strand). Ensembl gene ENSG00000085231.
Subcellular location: Cytoplasm; Nucleus, nucleoplasm; Nucleus, Cajal body
Subcellular location (Human Protein Atlas): Nuclear speckles; Centrosome
Pathways (Reactome):
Metabolism: Interconversion of nucleotide di- and triphosphates
Gene Ontology:
Molecular function: AMP kinase activity; protein binding; ATP binding; nucleoside monophosphate kinase activity; ATP hydrolysis activity
Biological process: nucleobase-containing small molecule interconversion; ribosomal small subunit biogenesis
Cellular component: Cajal body; membrane; nuclear speck; nucleolus; nucleoplasm; cytoplasm; nucleus
Genetic constraint (gnomAD): Loss-of-function variants: 24 observed, 24.51 expected, observed/expected ratio (o/e) 0.98, 90% interval 0.71 to 1.38. The upper end of that interval is the gene's LOEUF score, 1.38, which puts it in group 5 of 6, group 1 being the genes least tolerant of losing a copy. Missense variants: 191 observed, 207.65 expected, observed/expected ratio (o/e) 0.92, 90% interval 0.82 to 1.04. Synonymous variants: 73 observed, 73.44 expected, observed/expected ratio (o/e) 0.99, 90% interval 0.82 to 1.21.
Homologues: Orthologues: chimpanzee AK6 (100% identical), rabbit AK6 (90% identical), dog AK6 (90% identical), pig AK6 (85% identical), rabbit AK6 (85% identical), guinea pig AK6 (83% identical), rat Ak6 (82% identical), rat Ak6 (80% identical), tropical clawed frog ak6 (77% identical), zebrafish AK6 (75% identical), Caenorhabditis elegans E02H1.6 (49% identical), Drosophila melanogaster Ak6 (47% identical).
Diseases named in the same sentence as AK6 in open-access papers:
AK6 is named in the same sentence as 20 diseases in open-access papers, as found by Europe PMC text mining. Sharing a sentence is not in itself a finding about the gene and the disease. The quoted sentences say what the papers report.
colorectal cancer (6 papers, 2017 to 2026). A primary or metastatic malignant neoplasm that affects the colon or rectum. "Nevertheless, studies on human breast cancer and colorectal cancer demonstrated another AK isoform AK6 was overexpressed during cancer formation." (PMID 32509571, 2020). "In the case of colorectal cancer, the high AK6 is also correlated with a worse patient prognosis." (PMID 35712500, 2022). "Recently, the AK6 high expression level was found in breast cancer and colorectal cancer." (PMID 35712500, 2022). "However, only in cytosolic compartmentalized AK6 did expression level increase during tumorogenesis of breast and colorectal cancer cells." (PMID 32509571, 2020). "Furthermore, it was demonstrated that another AK isoform AK6 could affect colorectal cancer migration and invasion." (PMID 32509571, 2020).
breast carcinoma (3 papers, 2016 to 2025). "Focusing on the functions of these genes, the AK6 gene is crucial for embryonic development and is also associated with breast cancer formation." (PMID 40585860, 2025). "Analysis of the four AK genes (AK1, AK2, AK4, and AK6) mRNA expression in breast cancer cells revealed several alterations in the composition of the AK network." (PMID 35712500, 2022). "Despite the decreased overall phosphoryl flux, overexpression of HK2, AK2, and AK6 isoforms within cell compartments could promote aggressive breast cancer growth." (PMID 35712500, 2022).
colon cancer (3 papers, 2016 to 2022). "Moreover, experiments on colon cancer cell line SW480 and human testicular carcinoma NT2 revealed that AK6 gene silencing or overexpression suppressed or promoted cancer cells’ invasion potential, respectively." (PMID 35712500, 2022).
cervical cancer (2 papers, 2021 to 2023). A primary or metastatic malignant neoplasm involving the cervix. "Furthermore, the suppression of AK6 expression has been reported to reduce the migratory ability and EMT of cervical cancer cells under hypoxic conditions, indicating that it may be a potential therapeutic target for cervical cancer." (PMID 36982634, 2023).
prostate carcinoma (1 paper, 2022). A carcinoma that arises from epithelial cells of the prostate gland. "For example, IL9 was recently assigned as an essential gene in tumor immunity, and AK6 was already regarded as a biomarker in prostate cancer treatments." (PMID 36376815, 2022).
testicular cancer (1 paper, 2022). A primary or metastatic malignant neoplasm that affects the testis. "In human testicular cancer cells, the activity of volume-regulated chloride channel CLC3 is regulated by WNK1, which is activated by adenylate kinase 6 (AK6)." (PMID 36123332, 2022).
cancer (8 papers, 2016 to 2023). A tumor composed of atypical neoplastic, often pleomorphic cells that invade other tissues. "The loss of AK6 in fast-growing human cancer cells inhibits ribosome assembly and abolishes tumorigenesis." (PMID 36982634, 2023). "In humans, AK6 is known to be highly expressed in cancer and correlates with poor prognosis, and genome-wide polysome profiling has shown that hCINAP selectively regulates cancer-associated translatomes and promotes malignant transformation, making it a potential target for cancer therapy." (PMID 36982634, 2023). "Discovered overexpression of HK2, AK2, and AK6 isoforms in mitochondrial and nuclear compartments suggests that aggressive cancer cells use a strategy of microcompartmentation to support specific cellular functions and promote tumor growth." (PMID 35712500, 2022). "It was demonstrated that reduction of AK6 expression in cancer cells disrupts ribosome assembly and abolishes tumorigenesis of cancer cells." (PMID 35712500, 2022). "Specifically, we will overview how AK isoforms, localized in mitochondria (AK2 and AK4), and their main communication partners cytosolic AK (AK1 and AK6) are involved in cancer formation and metastasis." (PMID 32509571, 2020). "Studies indicate that AK isoforms (AK1, AK2, AK4, and AK6) have an important role in the regulation of cancer cell metabolism, metabolic signaling, and cell migration and invasion." (PMID 32509571, 2020). "Interestingly, when located at the cytosolic compartment, AK6 behaves as a metabolic modulator of the cancer cells." (PMID 35712500, 2022). "The nucleus isoform AK6 was identified as a human coilin-interacting nuclear ATPase protein hCINAP that regulates ribosomal RNA biogenesis and it was reported to be essential for embryogenesis, tumor growth, and self-renewal of cancer stem cells." (PMID 31444368, 2019). "Knockdown of AK6 can decrease the expression of WNK1 and CLC3, resulting in increased intracellular Cl− concentration in cancer cells upon hypotonic conditions." (PMID 36123332, 2022). "Recently, it was demonstrated that hCINAP or AK6 is a potent modulator of metabolic reprogramming by phosphorylating LDHA, a key player in cancer glycolysis." (PMID 32509571, 2020).
AK6 also shares sentences with these, for which no sentence is quoted: tumor (5 papers); acute myeloid leukemia (3); breast tumour (1); colon adenocarcinoma (1); colorectal adenocarcinoma (1); colorectal tumour (1); fatty liver (1); genetic disorder (1); hematological diseases (1); infertile (1); malnutrition (1); myelodysplastic syndrome (1); rectum adenocarcinoma (1).